IL6 (interleukin 6)
Diseases named in the same sentence as IL6 in open-access papers (continued):
Sharing a sentence is not in itself a finding about the gene and the disease.
breast cancer (continued). "Thus, blocking of IL-6R in breast cancer cells and neutralization of secreted IL-6 decreased STAT3 activity in breast cancer cells." (PMID 29891854, 2018). "In this study, autophagy was necessary for invasiveness and epithelial-to-mesenchymal transition in RAS-transformed MCF10A breast cancer cells and was also necessary for the secretion of proinvasive factors like IL-6, matrix-metalloproteinases 2 and 9, and WNT5A." (PMID 30622432, 2018). "Indeed, GPER was shown to cooperate with HIF-1α for the expression of invasive markers, including CTGF, VEGF and IL-6 in both breast cancer cells and CAFs exposed to low oxygen." (PMID 29996493, 2018). "We found that IL-6 secreted by adipocytes induce EMT in breast cancer cells." (PMID 29891854, 2018). "In addition, IL-6 has been shown to be a direct regulator for self-renewal of breast cancer cells through signal transducer and activator of transcription 3 (STAT3) activation mediated by the IL-6 receptor/GP130 complex." (PMID 29416638, 2018). "IL-6 also correlated with poor prognosis and advanced disease in breast cancer patients." (PMID 30083161, 2018). "Serum Shh and interleukin-6 (IL-6) could be useful prognostic biomarkers in progressive breast cancer." (PMID 29734730, 2018). "In addition, IL-6 was found to significantly induce the in vitro and in vivo growth of estrogen receptor (ER) positive breast cancer cells.The ability of IL-6 to promote breast cancer cell migration was also confirmed by our group." (PMID 29707128, 2018). "COX-2, TNF-α, VEGF-A and IL-6 are tumorigenic genes that are elevated in breast cancer." (PMID 30155724, 2018). "To further confirm whether IL-6 and leptin could induce PLOD2 expression, we treated MDA-MB-231 and MDA-MB-468 breast cancer cells with recombinant human IL-6 protein." (PMID 30563531, 2018). "In breast cancer bone metastasis, tumor-derived Jagged1 induces IL6 and TGFβ secretion from osteoblasts, which not only promotes tumor cell proliferation directly, but also induces osteoclasogenesis and therefore osteolysis, resulting in a further release of TGFβ." (PMID 29642534, 2018). "To identify a common paracrine signalling mechanism by which adipocyte induced EMT in breast cancer cell occur, we determined the expression of TGF-β and IL-6 (known regulator of EMT in breast cancer cells) in breast cancer cells and adipocytes after co-culture." (PMID 29891854, 2018). "In this regard, blockade of RANTES and IL-6 that can in turn interact with cancer cells or cells of the tumor microenvironment might prevent breast cancer progression." (PMID 29707128, 2018). "Furthermore, it has been observed that human breast cancer cell-derived exosomes induce the secretion of IL-6, TNFα, and CCL2 from both human THP-1 and murine RAW macrophage cell lines via the toll-like receptor 2/NF-κB signaling pathway." (PMID 29867925, 2018). "Importantly, the inhibitors reduced expression of the signature SASP factors IL-6 and IL-1α by cells made senescent by genotoxic stimuli, and suppressed the ability of senescent fibroblasts to stimulate breast cancer cell aggressiveness." (PMID 29402901, 2018). "This increased Twist expression also leads to IL-6 production by the breast cancer cells." (PMID 30487436, 2018). "The question whether inflammatory cytokines such as IL-6 cooperate with stromal-derived estrogen and sensitize breast cancer cells to ER, as we observe for testosterone signaling through the androgen receptor, remains to be determined." (PMID 29898754, 2018). "Importantly, in that study we found a role for the inflammatory cytokine IL-6 in sensitizing breast cancer cells to low testosterone levels." (PMID 29898754, 2018).
breast cancer (continued). "Thus far, we have demonstrated that IL-6 and leptin are increased in adipocytes and/or adipocytes cocultured with breast cancer cells." (PMID 30563531, 2018). "In this respect, studies in which IL-6 was shown to promote breast cancer cell proliferation used particular conditions in growth assays, such as 3D assays in which cells were embedded in a basement membrane extract, probably enriched with different growth factors." (PMID 29707128, 2018). "Our data provide evidence for the first time that the IL-6/STAT3 signalling pathway may be key regulatory pathway by which adipocytes affect breast cancer cell behaviour." (PMID 29891854, 2018). "We knockdown IL-6 in both adipocytes and breast cancer cells with an siRNA." (PMID 29891854, 2018). "In addition, IL-6 derived from metastatic CAFs triggered breast cancer growth in vitro and in vivo through the involvement of Notch-3, Jagged-1, and the HIF-1α target gene carbonic anhydrase IX." (PMID 29996493, 2018). "Taking together, these results suggests that IL-6 secreted by adipocytes may be a key regulator of the EMT program in breast cancer cells, vis alteration of EMT-TFs and EMT-related genes expression." (PMID 29891854, 2018). "Preclinical data support a role for the IL-6/JAK2/STAT3 signaling pathway in breast cancer." (PMID 29761158, 2018). "Adipocytes and breast cancer cells co-cultured had increased expression of IL-6." (PMID 29891854, 2018). "Interestingly, numerous studies demonstrated that cytokines and adipokines such as IL-6, IL-1β, TNFα and Leptin are major factors in breast cancer progression." (PMID 29930291, 2018). "Blocking IL-6 results in an increase in E-cadherin in both breast cancer cells." (PMID 29891854, 2018). "The IL-6/JAK-STAT3/Cyclin D1 axis is activated in biopsies from breast cancer patients." (PMID 30135434, 2018). "IL-6 is one of the main mediators of inflammation-induced stemness in breast cancer." (PMID 29721190, 2018). "Interestingly, two of the most up-regulated genes in the TN breast cancer cell line MDA-MB-231 following co-culture with adipocytes were IL8 and IL6, encoding the pro-inflammatory cytokines IL-8 and IL-6." (PMID 29930291, 2018). "Furthermore, blocking IL-6 signalling with siRNA and neutralising antibody in co-cultured breast cancer cells and adipocyte media, resulted in increased E-cadherin, and attenuation of EMT-related genes such as TWIST and N-cadherin." (PMID 29891854, 2018). "In addition, Gene Set Enrichment Analysis (GSEA) of Zeb1 depleted breast cancer cells showed its activating role in the expression of inflammatory response genes IL-6, IL-8, and IL-1α." (PMID 30483264, 2018). "Inhibition of IL-6/IL-6R with Dia displayed the similar effect in hypoxic breast cancer cells." (PMID 29695771, 2018). "Il-6 was only detected in basal-like breast carcinoma tissue which contained stem cell features." (PMID 30515368, 2018). "In this study, the IL-6-knockdown in the 4T1 murine mammary carcinoma cell line (4T1IL-6low) was successfully established to investigate the effects of tumor-derived IL-6 on the growth and invasion of breast cancer cells by infecting lentiviral shIL-6 into mammary carcinoma 4T1 cells." (PMID 30083161, 2018). "We have shown here, that both inflammatory cytokines IL6 and IL8 have the capability to induce typical stem-like cell properties (self-renewal and differentiation capabilities) associated with malignity in otherwise low aggressive breast cancer cells." (PMID 28472950, 2017). "Primary human breast tumor cells and human breast cancer cell lines can produce autocrine IL-6, suggesting that carcinoma cells may be the source of the increased levels of IL-6 in serum and tumors." (PMID 29088874, 2017). "Moreover, IL-6 promotes breast cancer bone metastasis through Notch-1, and induces mammosphere formation in breast cancer cells through Notch-3." (PMID 28270211, 2017).
breast cancer (continued). "The impact of inflammatory factors, such as IL-6, might also be of interest in the context of breast cancer cells possessing a hybrid epithelial/mesenchymal (E/M) or a partial EMT phenotype." (PMID 28768501, 2017). "Diet intervention and weight loss are an important strategy for reducing plasma IL-6, a risk factor of breast cancer in women, regardless of their rs1800795 genotype." (PMID 28555011, 2017). "Also, compared to NT controls, the expression of interleukin-6 (IL-6) and IL-8 mRNA was significantly reduced in breast cancer cells with disrupted VDR signaling." (PMID 28944088, 2017). "Correlations of interleukin-6 (IL-6) with clinicopathological features of breast cancer patients." (PMID 29326716, 2017). "Therefore, we detected IL-6 secretion in the supernatant of co-culture medium of breast cancer cells and CXCR2+ MDSCs." (PMID 29383101, 2017). "Interestingly, breast cancer patients treated with chemotherapy had significantly elevated IL-6 and TNF-α levels after approximately 5 years off-therapy, compared with healthy controls, with an interaction between these two cytokines." (PMID 28377717, 2017). "In a following study, we observed that upregulated hepcidin in the plasma of breast cancer patients is not directly associated with IL-6 augmentation." (PMID 28216608, 2017). "Additionally, our data provide evidence for the role played by Syndecan-1 in synchronously fine tuning multiple signaling pathways including IL-6/STAT3/gp130, inflammatory cytokines, Notch, and EGFR, implicated in breast cancer stemness." (PMID 28270211, 2017). "Therefore, blocking the IL-6 signaling pathway is a promising therapeutic strategy for eliminating and inhibiting MDSCs, as well as reversing MDSCs-mediated immune escape in breast cancer." (PMID 29326716, 2017). "Furthermore, CXCR2+ MDSC subsets induced breast cancer cells epithelial mesenchymal transition (EMT) via IL-6." (PMID 29383101, 2017). "Finally, we detected the same relationship among RB, hsa-miR-140 and IL-6 in a human breast cancer cell line MCF-7." (PMID 28099924, 2017). "Furthermore, it has been shown that adipocytes co-cultured with breast cancer cells exhibit decreased adiponectin concomitant with IL-6 overexpression." (PMID 28281525, 2017). "Likewise, exogenous IL-6 treatment also induces a significant increase in a cell’s invasive ability in MDA-MB-468 breast cancer cells." (PMID 28208810, 2017). "The expression of IL-6 in breast cancer cell lines was determined by RT-PCR." (PMID 28178994, 2017). "Furthermore, Pearson correlation analysis revealed a strong positive correlation between the expression of IL-6 mRNA and number of MDSCs in fresh breast cancer tissues (R2 = 0.4399, P = 0.0014)." (PMID 29326716, 2017). "High serum levels of IL-6 in breast cancer patients correlates with poor prognosis." (PMID 28966805, 2017). "Likewise, breast cancer cells under hypoxic conditions (1.5% O2) were able to secrete high levels of interleukin-6 (IL-6), which served to activate and attract MSCs through Stat3 and MAPK signaling pathways." (PMID 29069870, 2017). "Also, interleukin-6 that is secreted by the transformed fibroblasts induces tamoxifen resistance in luminal breast cancer." (PMID 28052038, 2017). "It is proposed that the inhibition of the AT1R, and its down-stream signaling through IL-6, could provide a promising treatment avenue for breast cancer, utilizing a well-characterized and tolerated class of ARB/ACEI drugs." (PMID 28416734, 2017). "Also, breast cancer patients had lower concentrations of adiponectin and higher concentrations of leptin, IL-6, IL-8, TNF-α, resistin and visfatin than controls." (PMID 29088874, 2017). "Regarding to the differences highlighted between colorectal and breast cancer patients, according to Kobayashi and Huang, colorectal cancer patients have higher IL-6 serum level, which in turn could lead to delayed hypersensitivity AEs." (PMID 28932193, 2017).
breast cancer (continued). "Collectively, these data suggest that IL-6 may enhance the migration ability of breast cancer cells." (PMID 28208810, 2017). "Furthermore, CXCR2+ MDSCs induce epithelial mesenchymal transition (EMT) of breast cancer cells via IL-6." (PMID 29383101, 2017). "Furthermore, PNA3 treatment of ovarian and breast cancer cells decreased (P < 0.05) IL-6 secretion into the media." (PMID 28420874, 2017). "However, the detailed function of Shp2 in IL-6-signaling-promoted breast cancer aggravation, remains uncertain." (PMID 28208810, 2017). "The role of adipokines was demonstrated by Dirat et al141 who reported increased invasiveness of both human and murine breast cancer cells associated with overexpression of proteases, including MMP-11, and pro-inflammatory cytokines (IL-6, IL-1β), when cocultured with adipocytes." (PMID 29104428, 2017). "In addition, an IL6 inflammatory loop has been reported to expand the cancer stem cell population in HER2-positive breast cancer and lead to trastuzumab resistance." (PMID 27447863, 2017). "This is in clear contrast with other cell lines, including the MDA-MB-231 basal breast cancer subtype, which expresses high IL6 and IL8 levels and are categorized as immortalized-cell progenitor subtype with limited differentiation potential and negative for SA-βGal." (PMID 28472950, 2017). "Indeed, basal/mesenchymal breast cancers that constitutively express IL6 and IL8 have been shown to be more aggressive than luminal cancers." (PMID 28472950, 2017). "To determine whether Shp2 is involved in regulating the invasion and migration of breast cancer cells induced by IL-6, we knocked down Shp2 by using a specific siRNA in the T47D cell line." (PMID 28208810, 2017). "Moreover, several studies have shown that IL-6/STAT3 signaling is required for the growth of CD44+CD24− stem-cell-like breast cancer cells and for the dynamic equilibrium of breast CSCs." (PMID 27609180, 2016). "Finally, we defined the molecular basis of radiation-induced EMT in breast cancer cells, finding that it results from the fact that Notch2 upregulation is accompanied by IL-6-dependent STAT3 activation." (PMID 27462787, 2016). "Additionally, PAC suppressed the paracrine procarcinogenic effects of breast cancer cells on breast stromal fibroblasts via suppressing the secretion of two important cytokines IL-6 and MCP-1." (PMID 27465411, 2016). "Taken together, these results provide evidence that, when the survival signal of breast cancer cells is switched from HER2 to IL-6 signaling, lapatinib resistance may be acquired." (PMID 27694691, 2016). "Moreover, we uncovered the mechanism of Notch-driven EMT, in which Notch enhanced EMT through IL-6/JAK/STAT3 signaling axis in mammary tumor cells." (PMID 27462787, 2016). "Data from epidemiological studies is also accruing in support of a contributory role of elevated circulating IL-6 in patients with advanced tumour stages and aggressive behaviour of various cancers, such as non-small-cell lung cancer, colorectal cancer, breast cancer, and renal cell carcinoma." (PMID 27034885, 2016). "Hsa-miR-365 is over-expressed in human breast cancer which down-regulates IL-6 in HeLa cells." (PMID 27786176, 2016). "Furthermore, we find that radiation-induced IL-6 secretion serves as a major contributor to Notch-induced EMT in breast cancer cells in response to the fractionated radiation." (PMID 27462787, 2016). "In this study, we confirmed that acquired lapatinib-resistant HER2-positive breast cancer cells had elevated IL-6, and that elevated IL-6 maintained the stemness population and property within these resistant cells through the activation of signal transducer and activator of transcription 3 (STAT3)." (PMID 27694691, 2016). "Accumulating evidence show the contribution of IL-6 to the progression of breast cancers." (PMID 27602583, 2016).
breast cancer (continued). "Additionally, based on the detection of EDU and PCNA, A1CF (-8aa) promotes cell proliferation via upregulating the expression of IL-6 in basal-like breast cancer cells (MAD-MB-231)." (PMID 27231908, 2016). "With an increased understanding of the IL-6/IL-6R/gp130 regulatory axis and signaling in breast cancer, it may be possible to design new IL-6 therapies which will be more effective." (PMID 26840088, 2016). "This may be due to alternate signaling pathways such as the IL6/CXCL7 loop reported in breast cancer." (PMID 26755648, 2016). "In this review, we summarize the structures, preclinical and clinical studies, mechanisms of action of chemical and biological blockers that directly bind to IL-6, IL-6R, or gp130, and the potential clinical applications of these pharmacological agents as breast cancer therapies." (PMID 26840088, 2016). "Hence, the aim of this study was to evaluate the associations between pro-inflammatory cytokine gene polymorphisms namely, IL6-174 (rs1800795 G>C) and TNF-308 (rs1800629 G>A), and CACI among early-stage breast cancer patients in Singapore." (PMID 27701469, 2016). "Apart from IL-6, reduced levels of all macrophage-associated cytokines were observed in C3HBA tumors in Chy mice, indicating an impaired innate immune response and potentially influencing the early stages of breast cancer progression." (PMID 27329584, 2016). "However, preclinical and clinical studies of the applications of anti–IL-6/IL-6R/gp130 therapy in breast cancers are limited." (PMID 26840088, 2016). "The three breast cancer subtypes rely on IL-6 signaling to varying degrees." (PMID 26840088, 2016). "In this study, we demonstrate that different breast cancer cell lines after treatment with clinically relevant concentrations of 5-fluorouracil, doxorubicin, or paclitaxel enrich CSCs, increase expression of IL-6, IL-8, and MCP-1 cytokines, and up-regulate activation of NF-κB and Stat3 pathways." (PMID 26506421, 2016). "An interleukin 6 (IL-6) neutralising antibody is currently undergoing evaluation in clinical trials, and neutralising antibodies against human chemokines have shown promising results in preclinical models of prostate and breast cancer." (PMID 26784251, 2016). "In one study of 20 breast cancer patients and 23 healthy controls, left hippocampal volumes were reduced significantly and IL-6 and TNF-α concentrations elevated in the breast cancer group and lower left hippocampal volume was associated with higher circulating TNF-α and lower IL-6." (PMID 27047716, 2016). "IL-6 have been demonstrated to regulate the self-renewal in breast CSCs, triggering malignant features in ductal breast carcinoma and mediating drug resistance in breast cancer cells by expanding CSC population." (PMID 27285760, 2016). "Breast cancer cells can secrete IL-6 and IL-8 in response to IL-1α." (PMID 27169366, 2016). "Furthermore, elevated levels of serum IL-6 correlated with poor prognosis of breast cancer patients." (PMID 27248826, 2016). "However, it is of interest that clinical trials evaluating Il-6/JAK/ STAT inhibitors in breast cancer patients are under way." (PMID 27769057, 2016). "Furthermore, IL6-mediated suppression of miR200c drives the transformation of breast cancer cells, and activation of an IL6 inflammatory feedback loop leads to expansion of cancer stem cell population in malignant carcinomas." (PMID 27285760, 2016). "In this study, we found that long-term treatment of lapatinib in HER2-positive breast cancer cells led to increased IL6 expression, subsequent activation of downstream STAT3 signaling, and the maintenance of stemness, all of which contributed to acquired lapatinib resistance." (PMID 27694691, 2016). "Therefore, given that clinical trials evaluating Il-6/JAK/ STAT inhibitors in breast cancer patients are under way, it would be important to determine the role of STAT1 and STAT3 in this disease." (PMID 27769057, 2016).